SCLY (selenocysteine lyase)
Description:
Catalyzes the decomposition of L-selenocysteine to L-alanine and elemental selenium.
Synonyms: hSCL; SCL
Tractability: Small molecule: a structure with a bound ligand is known; it has a high-quality binding pocket. PROTAC: ubiquitination databases record sites on it; its protein half-life has been measured.
Target class: Enzyme; Lyase
Gene: Protein-coding gene on chromosome 2 (238,060,924 to 238,099,413, forward strand). Ensembl gene ENSG00000132330.
Subcellular location: Cytoplasm, cytosol
Subcellular location (Human Protein Atlas): Golgi apparatus
Pathways (Reactome):
Metabolism: Metabolism of ingested SeMet, Sec, MeSec into H2Se
Gene Ontology:
Molecular function: protein binding; selenocysteine lyase activity; amino acid binding; protein homodimerization activity; vitamin B6 binding
Biological process: amino acid metabolic process
Cellular component: Golgi apparatus; cytosol; catalytic complex
Genetic constraint (gnomAD): Loss-of-function variants: 26 observed, 34.54 expected, observed/expected ratio (o/e) 0.75, 90% interval 0.55 to 1.04. The upper end of that interval is the gene's LOEUF score, 1.04, which puts it in group 4 of 6, group 1 being the genes least tolerant of losing a copy. Missense variants: 516 observed, 533.65 expected, observed/expected ratio (o/e) 0.97, 90% interval 0.9 to 1.04. Synonymous variants: 216 observed, 214.47 expected, observed/expected ratio (o/e) 1.01, 90% interval 0.9 to 1.13.
Homologues: Orthologues: chimpanzee SCLY (99% identical), macaque SCLY (96% identical), dog SCLY (83% identical), guinea pig SCLY (78% identical), mouse Scly (77% identical), rat Scly (77% identical), pig SCLY (77% identical), tropical clawed frog scly (59% identical), zebrafish scly (59% identical), Caenorhabditis elegans scly-1 (38% identical). Paralogues in human: NFS1 (33% identical).
Diseases named in the same sentence as SCLY in open-access papers:
SCLY is named in the same sentence as 17 diseases in open-access papers, as found by Europe PMC text mining. Sharing a sentence is not in itself a finding about the gene and the disease. The quoted sentences say what the papers report.
Obesity (4 papers, 2018 to 2022). Accumulation of substantial excess body fat. "Whole-body knockout of the selenium recycling enzyme, selenocysteine lyase (Scly), increases susceptibility to metabolic syndrome and diet-induced obesity in mice." (PMID 31340540, 2019). "The downregulation of SCLY suggests a change in Se sources for selenoprotein synthesis occurs in NAFLD livers, further implicating SCLY as a potential target or localized biomarker for obesity-induced cancers, particularly in the liver." (PMID 36358931, 2022). "Disruption of the Scly gene in mice led to obesity, hyperinsulinemia, glucose intolerance, and hepatic steatosis, with SCLY being suggested as a participant in the regulation of energy metabolism in a sex-dependent manner." (PMID 31480609, 2019). "Male Scly−/− mice also worsened their obesity when fed a high-fat diet, even when dietary selenium levels were adequate, suggesting that the role of SCLY in energy metabolism could be independent of its involvement in selenoprotein biosynthesis." (PMID 31480609, 2019).
dyslipidemia (2 papers, 2018 to 2019). "Disruption of the selenocysteine lyase gene (Scly) in mice (Scly−/− or Scly KO) led to obesity with dyslipidemia, hyperinsulinemia, glucose intolerance and lipid accumulation in the hepatocytes." (PMID 31717805, 2019).
selenium deficiency (2 papers, 2021). A nutritional deficiency disease resulting from inadequate selenium levels in the body, which can lead to impaired function of selenoproteins essential for antioxidant defense and thyroid hormone metabolism. "Moreover, mice lacking Scly, which encodes the Sec-decomposing enzyme SCLY that participates in selenoprotein synthesis and degradation, develop obesity with impaired hepatic energy metabolism and redox status, and localized selenium deficiency." (PMID 34204631, 2021). "Interestingly, mice lacking SCLY develop hepatic steatosis, which is aggravated by selenium deficiency and not restored by selenium supplementation; it is unknown if this mouse model develops NASH as it ages." (PMID 34869521, 2021).
Hepatic steatosis (1 paper, 2021). Steatosis is a term used to denote lipid accumulation within hepatocytes. "The hepatic steatosis presented by the homozygous SCLY knockout mouse model informs that downregulation of SCLY may also be implicated in NAFLD development in humans." (PMID 34869521, 2021).
cancer (3 papers, 2019 to 2022). A tumor composed of atypical neoplastic, often pleomorphic cells that invade other tissues. "Despite uncovering an association of SCLY with these carcinomas, the sole use of bioinformatics approaches without wet lab confirmation to investigate several selenoproteins and their association with the top five most common cancers limits the conclusions for this study." (PMID 36358931, 2022). "SCLY may contribute to the Warburg metabolic switch in cancer cells by controlling selenoprotein synthesis, particularly the ones participating in energy metabolism and controlling carbohydrate or lipid utilization." (PMID 36358931, 2022). "Therefore, the participation of SCLY in gauging energy metabolism via the control of Se flux to selenoprotein synthesis turns this enzyme into a potential target in cancer research." (PMID 36358931, 2022). "Thus, impairing this route of selenocysteinyl-tRNA formation in conjunction with xCT inhibition could have even more potent effects, and the potential functions of SCLY in cancer and ferroptosis should be explored in future studies." (PMID 33672555, 2021). "Nevertheless, the specific role of SCLY in the tumorigenesis and progression of cancers derived from NAFLD or NASH, particularly at the early stages of cancer development, remains undetermined." (PMID 36358931, 2022). "Cancer cells may increase the uptake of Se through system Xc− or as SELENOP through LRP8 receptor to protect the cell from ferroptotic cell death, while also modulating key enzymes of the trans-selenation pathway, such as CBS, CGL, or SCLY." (PMID 36358931, 2022). "Aside from the hijacking of the xCT transporter to promote intake of Se and Sec instead of cysteine in certain cancer cells, there are enzymes involved in the metabolism of Se, such as CGL, CBS, and SCLY, that may have roles in cancer cell survival and/or proliferation." (PMID 36358931, 2022). "Unlike CGL and CBS, the role of SCLY in cancer is poorly understood." (PMID 36358931, 2022).
tumor (3 papers, 2022 to 2025). "Multi-omics analyses revealed consistently elevated expression of AHCY, BUD23, LCMT1, MARS1, METTL6, SCLY and SEPHS1 in various tumor types." (PMID 41441975, 2025).
SCLY also shares sentences with these, for which no sentence is quoted: Glucose intolerance (2 papers); Hyperinsulinemia (2); breast carcinoma (1); colon cancer (1); congestive cardiomyopathy (1); depression (1); insomnia (1); leukemia (1); melanoma (1); prostate carcinoma (1); renal carcinoma (1).